TCHH (trichohyalin)
Description:
Intermediate filament-associated protein that associates in regular arrays with keratin intermediate filaments (KIF) of the inner root sheath cells of the hair follicle and the granular layer of the epidermis. It later becomes cross-linked to KIF by isodipeptide bonds. It may serve as scaffold protein, together with involucrin, in the organization of the cell envelope or even anchor the cell envelope to the KIF network. It may be involved in its own calcium-dependent postsynthetic processing during terminal differentiation.
Synonyms: THH; THL; TRHY; UHS3
Tractability: Antibody: its Gene Ontology location is reachable by antibodies, with high confidence. PROTAC: ubiquitination databases record sites on it.
Gene: Protein-coding gene on chromosome 1 (152,106,317 to 152,115,444, reverse strand). Ensembl gene ENSG00000159450.
Pathways (Reactome):
Developmental Biology: Formation of the cornified envelope
Gene Ontology:
Molecular function: calcium ion binding; protein-macromolecule adaptor activity; transition metal ion binding
Biological process: intermediate filament organization
Cellular component: cornified envelope; cytoskeleton; cytosol
Genetic constraint (gnomAD): Loss-of-function variants: 11 observed, 9.32 expected, observed/expected ratio (o/e) 1.18, 90% interval 0.74 to 1.81. That is too few expected variants to judge how well the gene tolerates losing a copy. Missense variants: 2,917 observed, 2,521.5 expected, observed/expected ratio (o/e) 1.16, 90% interval 1.12 to 1.19. Synonymous variants: 1,087 observed, 974.46 expected, observed/expected ratio (o/e) 1.12, 90% interval 1.06 to 1.17.
Homologues: Orthologues: macaque TCHH (73% identical), mouse Tchh (36% identical).
Diseases named in the same sentence as TCHH in open-access papers:
TCHH is named in the same sentence as 21 diseases in open-access papers, as found by Europe PMC text mining. Sharing a sentence is not in itself a finding about the gene and the disease. The quoted sentences say what the papers report.
uncombable hair syndrome (4 papers, 2017 to 2024). Uncombable hair syndrome (UHS), or pili trianguli et canaliculi, is a rare scalp hair shaft dysplasia. "The involvement of TCHH in hair morphology is further supported by the previous discovery of a rare nonsense mutation (rs201930497) in Europeans leading to uncombable hair syndrome (UHS) with a curly hair phenotype." (PMID 35371514, 2022). "Other downregulated genes, namely PADI3 and TCHH are associated with uncombable hair syndrome in humans and S100A3 has been connected with an age-dependent damage of the hair cuticle." (PMID 30794648, 2019). "According to the ACMG standards, 75% of these variants were variants of uncertain significance (Class 3); two pathogenic (Class 5) variants were identified in TCHH and LSS, genes associated with uncombable hair syndrome, and macrocephaly, alopecia, cutis laxa, and scoliosis, respectively." (PMID 38791074, 2024).
autoimmune disorders (1 paper, 2022). "TCHH is also subjected to transglutaminase-mediated deamidation, which suggests similarities with other deamidation-mediated autoimmune disorders (e.g., celiac disease)." (PMID 35720384, 2022).
bladder cancer (1 paper, 2020). "For example, over-expression of TCHH, which encodes trichohyalin, a structural protein that binds keratin fibres, has been linked with sensitivity to tyrosine kinase inhibition in bladder cancer." (PMID 32734521, 2020).
colorectal cancer (1 paper, 2023). A primary or metastatic malignant neoplasm that affects the colon or rectum. "TCHH methylation might play a potential role in the induced pluripotent stem cell (iPSC) differentiation, a higher level of TCHH methylation is observed in colorectal cancer liver metastasis sites and exhibits an association with tumor volume." (PMID 36512456, 2023).
dermatitis (1 paper, 2024). An inflammatory process affecting the skin. "This is the first study to report on trichohyalin gene expression in canine AD and to correlate gene expression with the severity of dermatitis." (PMID 39234173, 2024).
glioma (1 paper, 2022). A benign or malignant brain and spinal cord tumor that arises from glial cells (astrocytes, oligodendrocytes, ependymal cells). "Interestingly, not much is known about the functions of OTUD1, TCHH, ADPRH, PLBD1, and QPCT in glioma, which need further research in future." (PMID 36389681, 2022).
urothelial carcinoma (1 paper, 2023). A malignant neoplasm derived from the transitional epithelium of the urinary tract (urinary bladder, ureter, urethra, or renal pelvis). "Among genes recorded in “Pathology” section in THPA, staining intensities of AKR1B1, TCHH, AKAP12, and IGF2 are distinctly higher in tissues from urothelial carcinoma than in normal bladder." (PMID 36512456, 2023).
tumor (6 papers, 2015 to 2026). "Among the genes that are mutated between 5 to 20% in TCGA GBM tumor samples, we found mutations in NF1, SPTA1, TCHH and ATRX genes, although, the other genes like PIK3R1, PIK3CA, RB1, IDH1 and KEL were not mutated in any cell line." (PMID 26496030, 2015). "Conversely, genes related to epithelial differentiation and keratinization (FLG, FLG2, HRNR, TCHH, KRT73), immune regulation and tumor suppression (HLA-G, UNC5D), and metabolic signaling were downregulated, reflecting loss of tissue integrity and immune control." (PMID 41900972, 2026).
TCHH also shares sentences with these, for which no sentence is quoted: alopecia (1 paper); asthma (1); atopic dermatitis (1); breast carcinoma (1); cancer (1); childhood onset asthma (1); cutis laxa (1); hair disorder (1); infection (1); Macrocephaly (1); neurodegenerative disease (1); rheumatoid arthritis (1); scoliosis (1).